EGFR (epidermal growth factor receptor)
Diseases named in the same sentence as EGFR in open-access papers (continued):
Sharing a sentence is not in itself a finding about the gene and the disease.
cancer (continued). "Since PI3K-associated signaling was shown to control drug efflux transporter BCRP levels in cancer cells, miR-206-induced c-MET/EGFR inhibition might affect BCRP in our cell system." (PMID 29291022, 2017). "In other cancers, NTS induces the autocrine activation of EGFR mediated through EGF “like” ligands." (PMID 28316623, 2017). "Moreover, we found that signaling mediated by the epidermal growth factor receptor (EGFR) participates in MYBL2 and A3B expression in cancer cells." (PMID 28276478, 2017). "Recently, a novel EGFR extracellular domain deletion mutant EGFRΔ768 has been found in primary tumors of NB patients and in a NB cell line BE2M17, which confers an aggressive cancer phenotype in NB cells." (PMID 27902463, 2017). "On the other side of the disease spectrum, chemotherapy and biological therapy against epidermal growth factor receptor (EGFR) and vascular endothelial growth factor (VEGF) are the primary treatments for advanced diseases; however, cancer cells commonly become refractory to these agents." (PMID 28146084, 2017). "Analogous experiments showed that PC-PLC also co-immunoprecipitated with EGFR, suggesting that the phospholipase could form complexes with the two ErbB receptors overexpressed in these cancer cells and/or with HER2/EGFR heterodimers." (PMID 28903399, 2017). "In the case of cetuximab, this is supported by the observations that even though it interfered with growth signals, it did not induce cell death, probably because of activation of alternative survival pathways in cancer cells independent of the EGFR." (PMID 28611673, 2017). "Some researchers have suggested that COX-2 is induced by LMP-1 and contributes to the cancer process via the co-expression with VEGF, EGFR or other biomarkers which could enhance several cell survival and proliferation signal pathways." (PMID 28301518, 2017). "Various evidences showed that CD147 might enhance the migration and metastasis of cancer via Annexin A2/DOCK3-β-catenin- WAVE2, EGFR-src-Rac1-pSTAT3-DOCK8, integrin-FAK-PI3K/PIP3-Rac1-WAVE2 and FAK- PI3K/PIP3-Rac1-WAVE2 pathways." (PMID 29163835, 2017). "Among the genes upregulated by EGFR internalization, increased expression of COX-2, the key enzyme in PGE2 biosynthesis, indicates a positive feedback loop between PGE2/EGFR and COX-2, an instrumental regulatory circuit for the amplification of malignant tumor progression." (PMID 28415726, 2017). "Nevertheless, activation of the EGFR drove cancer progression via complex mechanisms, which were not well understood." (PMID 29137265, 2017). "The same phosphorylated protein could be enriched into different signaling pathways, for example the phosphorylated EGFR could be enriched in pathways including HIF-1, MAPK, PI3K/Akt, Ras, FoxO and Central carbon metabolism in cancer." (PMID 29018223, 2017). "Overall, our findings suggest that agents targeting EGFR/HER2 could inhibit the induction of PD-L1, which may be dependent on the PI3K-AKT-mTOR pathway and suppress cytokines release in HER2-amplified cancer cells." (PMID 28969039, 2017). "Therefore, the combined inhibition of both EGFR and VEGFR-2 has thereby simultaneously become an efficient approach to cancer treatment with a synergistic effect." (PMID 29295519, 2017). "We intended to transport the catalytic part of this toxin preferentially into cancer cells using a toxin transporter (Protective antigen, PA) which was redirected to Epidermal Growth Factor Receptors (EGFR) or to human EGF receptors 2 (HER2), which are overexpressed in several cancer cells." (PMID 28128281, 2017). "In the absence of 4-OHT both clinically approved anti-EGFR antibodies, cetuximab and panitumumab, effectively inhibited proliferation and clonogenic survival of Difi cancer cells in vitro." (PMID 28507280, 2017).
cancer (continued). "We characterized expression of Syndecan-1 and the CSC marker CD44, Notch-1 & -3 and EGFR in carcinoma tissues of triple negative IBC (n = 13) and non-IBC (n = 17) patients using qPCR and immunohistochemistry." (PMID 28270211, 2017). "In this study, we examined the expression of Syndecan-1 and its correlation with the CSC marker CD44, Notch-1 & -3 and EGFR expression in carcinoma tissues of triple negative IBC and non-IBC patients." (PMID 28270211, 2017). "The location of the primary tumor, age, sex, histology of cancer cells, presence of lymphatic/perineural invasion, KRAS and BRAF mutation, or EGFR and ERBB2 expression did not significantly influence the success of PDC establishment." (PMID 26909603, 2016). "In addition to the potential use of FAM83A as a biomarker, a forward genetic screen identified FAM83A as a driver of EGFR tyrosine kinase inhibitor (TKI) resistance, suggesting FAM83A plays an important role in cancer cell biology." (PMID 27221039, 2016). "This notion was further corroborated by the finding that survival of cancer cells is maintained by EGFR independent of its kinase activity." (PMID 30370422, 2016). "EGF or HB-EGF have also been conjugated to other toxin fragments, with EGF-PE, EGF-ricin, EGF-saporin, and HBEGF-saporin also showing specific toxicity to EGFR-expressing cancers in vitro or in vivo while remaining mostly non-toxic to healthy cells." (PMID 27153091, 2016). "The MET and EGFR tyrosine kinases are actionable therapeutic targets due to their high expression in TNBC and availability of several selective kinase inhibitors that are either FDA approved for other cancers or are in clinical trials." (PMID 27655711, 2016). "In this study, we found that ctDNA with a genotype different from that of the major cancer cell population appeared upon initiation of EGFR-TKI or radiation therapy, then disappeared and did not appear again during the observation period." (PMID 27934896, 2016). "Combination therapy for cancer featuring HDAC inhibitors and other targeted inhibitors, such as EGFR inhibitors, may enhance treatment efficacy and improve survival times." (PMID 27449083, 2016). "Second, flux-driven sialylation did not alter EGFR dimerization as has been reported for cancer cell lines that experience increased sialylation due to spontaneous mutations." (PMID 27613843, 2016). "Our results demonstrate that dasatinib, but not EGFR-directed treatment, can decrease cell viability of stromal cancer stem cells less sensitive to doxorubicin." (PMID 26788073, 2016). "The interesting part of REG4 is that it is able to activate EGFR pathway, in the meantime, REG4 mRNA can be induced by some EGFR ligands, which suggests that a positive feedback loop of REG4 regulation is likely to exist in cancer tissues." (PMID 27036049, 2016). "MET activation promotes the cancer stem cell phenotype and HGF/MET signaling plays a crucial role in the development of resistance to classical cytotoxic therapy and targeted therapy, such as EGFR and BRAF inhibitors." (PMID 27121052, 2016). "We have recently shown that small NBD compounds enhance EGFR phosphorylation in the absence of a cognate ligand and thereby trigger aberrant signaling in cancer cells." (PMID 26883293, 2016). "In cancer cells, EGFR aberrations impact a variety of cell signaling pathways, notably the PI3K-AKT and JAK/STAT pathways." (PMID 27830833, 2016). "However, we noted that both EGFR and KLF4 mRNAs are known targets of microRNA-7 (miR-7) in human cancer cells." (PMID 26840086, 2016). "Other investigations also indicated that EGFR and the dimerization inducer HER-3 may provide compensatory signals for cancer cells to escape targeted therapies in the liver." (PMID 27031829, 2016). "Moreover, E1A has been shown to downregulate RTKs, such as EGFR, HER2/neu or AXL, and accumulating evidence has indicated that RTKs play important roles in cancer progression." (PMID 27590506, 2016).
cancer (continued). "The diversity of GPCR, its heterogeneous expression in cancer and its complex cross signaling via GPCR-mediated EGFR-transactivation as discussed in this review may help explain this suboptimal clinical response." (PMID 27187360, 2016). "Such smart targeted nanoparticles have the preference to release the drug intracellularly rather than into the bloodstream, and specifically recognize and kill cancer cells that overexpress EGFR while being non-toxic to EGFR-negative cells." (PMID 27833124, 2016). "First, we sought to determine whether protein expression of EGFR, ERBB3 and CDKN1B, could be used to predict differential sensitivity to anti-cancer drugs in HER2+ cancers." (PMID 27035903, 2016). "Both EGFR and AXL play important role in cancer progression and are related to poor prognosis." (PMID 27590506, 2016). "Some studies have suggested CD73 promotes cancer cells proliferation via other molecules, independent of adenosine, such as EGFR." (PMID 27557512, 2016). "Tamoxifen resistance is a complex progress involving the inappropriate activation of ER-mediated epidermal growth factor receptor (EGFR) signaling pathway which promotes the proliferation and survival of cancer cells, rendering them cancer stem cell-like properties." (PMID 27977766, 2016). "Moreover, EGFR is a direct activator of ERK oncogenic signaling, which promotes cancer progression by stimulating cell proliferation, apoptosis, metabolism, and angiogenesis." (PMID 27542224, 2016). "In the current study, we identify a specific molecular interaction between EGFR and IGF-1R that may play a role in resistance to cetuximab, the leading anti-EGFR inhibitory agent in current clinical use for cancer therapy." (PMID 27716204, 2016). "In contrast, the luminal miRNAs targeted transcription factors that controlled EMT (ZEB1/2), and biomarkers associated with fibrosis and actin cytoskeleton (collagens), and basal cancer biology (IL6, EGFR, STAT3), all of which are suppressed in luminal cancers." (PMID 27845906, 2016). "Both MET and EGFR are successful therapeutic targets in other cancers, yet have not been thoroughly tested in TNBC." (PMID 27655711, 2016). "The findings reported here also indicate that inhibitors of HGF activation overcome primary and acquired resistance to anti-EGFR therapy, providing a rationale for concurrent inhibition of EGFR and HGF to prevent therapeutic resistance and to improve the outcome of cancer patients." (PMID 27121052, 2016). "As with EGFR, increased expression of HER3 is seen in several cancer forms and although it has a severely impaired intrinsic tyrosine kinase activity, making heterodimerization with other HER family members essential, HER3 has been demonstrated to function as a, possibly HER2-dependent, oncogene." (PMID 26844548, 2016). "The drugs included in the screening library are low molecular weight protein kinase inhibitors (KI) targeting receptor tyrosine kinases (RTK), e.g. EGFR, and intracellular kinase pathways, e.g. PKC, considered important in cancer cell proliferation and/or survival." (PMID 27286453, 2016). "Although sialylation is induced to suppress the phosphorylation of EGFR, the effect of suppression was not strong enough to inhibit the downstream signaling necessary for cancer progression." (PMID 27029067, 2016). "TAMs may also secrete EGF-like ligands/factors that activate the EGFR pathway in cancer cells, thus promoting EMT, and this macrophage-induced EMT is significantly inhibited by treatment of A549 cancer cells with JWH-015." (PMID 27975071, 2016). "At multivariate analysis, ECOG-PS≥2, stage IV cancer, non-adenocarcinoma histology, EGFR wild-type status and NLR were predictors of worse OS." (PMID 27029035, 2016). "In addition to targeting CCND3, hsa-miR-16-5p is also known to regulate the expression of various angiogenic (e.g., PTGS2, VEGF, FGFR) and/or carcinogenic factors (e.g. EGFR, BMP7, MAPKs) with key roles in cancer/disease signaling pathways." (PMID 26930275, 2016).
cancer (continued). "Our preliminary data show that antibody intrinsic affinity to the target antigen clearly regulates the ability of affinity-modulated anti-EGFR and anti-HER2 antibodies to induce CDC in cancer cell lines previously shown to be resistant to complement-mediated attack (manuscript in preparation)." (PMID 27322177, 2016). "Theoretically, the combination of EGFR-TKI and ginsenoside Rg3 may exert not only a synergistic anti-cancer effect, but also a synchronous inhibitory effect on EGFR and VEGF signaling pathways." (PMID 27655708, 2016). "In addition, epidermal growth factor receptor (EGFR), which plays an important role in tumorigenesis, is overexpressed in many types of cancers, especially in CRC." (PMID 27729020, 2016). "EGFR expression was determined immunohistochemically on the surface and in the cytoplasm of cancer cells within resected tissues, but none was observed in the surrounding stroma." (PMID 27399694, 2016). "Several groups have reported that EMT could induce cancer cell resistance to EGFR-TKI, whereas restoring E-cadherin expression increased cancer cell sensitivity to EGFR-TKIs." (PMID 27455225, 2016). "EGF stimulated AREG production was tightly regulated in normal and transformed cell lines, suggesting that failure to control EGFR induced AREG expression may be a crucial step in carcinogenesis and cancer progression." (PMID 27669890, 2016). "Despite effective targeting of the CSC population, our data suggested that inhibiting EGFR by Cetuximab in combination with Ixabepilone did not have significant anti-cancer effects in TNBC tumors." (PMID 26757880, 2016). "First, the clinical efficacy of inhibiting a ligand-receptor interaction with antibodies has been clearly demonstrated in the Receptor Tyrosine Kinase (RTK) pathway field with clinically validated antibodies inhibiting HER2, EGFR, VEGFR, PDGFR and FGFR signaling in numerous cancers." (PMID 27598201, 2016). "The epidermal growth factor receptor HER2/neu is expressed on various cancers and represents a negative prognostic marker, but is also a target for the therapeutic monoclonal antibody Trastuzumab." (PMID 26887048, 2016). "The prognosis of patients with EGFR-positive/HPV-negative cancer was the poorest, while the EGFR negative/HPV-positive group showed the best outcome." (PMID 27556186, 2016). "It is particularly interesting that no IPF patients had EGFR mutation-positive cancers, which has been shown for the first time although a previous study has reported a correlation between preexisting ILD and EGFR-WT adenocarcinoma." (PMID 27350261, 2016). "Studies have reported that heparin-binding EGF (HB-EGF) can bind to EGFR when mediated by sulfated HSPG, thereby promoting sustained phosphorylation of EGFR on Tyr1068 and Tyr992 residues and activating the downstream AKT and ERK signaling pathways to promote cancer cell proliferation and migration." (PMID 27806323, 2016). "Altogether, our study not only identified a new biological role of CTSS in EGFR signalling regulation, but also provided a mechanical rationale to combine a CTSS inhibitor and an EGFR tyrosine kinase inhibitor for treating cancer through EGFR expression in the future." (PMID 27387133, 2016). "In addition to EGFR-TKI, AXL also induced resistance to other targeted therapies or chemotherapy in multiple types of cancer." (PMID 27590506, 2016). "However, EGFR can also bind with MET and PDGFR, thereby constituting a diversified signal transduction network in cancer cells." (PMID 27013592, 2016). "Over-expression of epidermal growth factor receptor (EGFR) gene amplifications is associated with many types of cancers, including NPC, and the positive-expression rate of EGFR is more than 90% in non-keratinizing NPC." (PMID 27955638, 2016). "Histologically, these areas correspond to mature, differentiated keratinizing cancer cells that expressed moderate levels of EGFR, yet did not incorporate the antibody-dye conjugate." (PMID 26120042, 2015).
cancer (continued). "This suggested that the EGFR signaling pathway acts as an upstream regulator for HIF-1α and that targeting EGFR may be beneficial for cancer treatment by affecting HIF-1α expression and translocation." (PMID 25997612, 2015). "HGF makes the cancer cells independent of EGFR signaling and enables EGFR to interact with other proteins such as CUB domain-containing protein-1 (CDCP1), EphA2 and AXL, forming a c-Met (HGFR)-EGFR cross-talk that can't be inhibited by EGFR TKI treatment." (PMID 26405162, 2015). "Importantly, HDN-1 degrades multiple client proteins, such as EGFR, Stat3, Akt, Erk, Raf, Cyclin D1, and HIF, all of which have been reported to be oncoproteins to promote cancer development." (PMID 25742791, 2015). "An increase in GPC has been observed with various chemotherapeutic and targeted anti-cancer agents, thus it is unlikely to be specific to EGFR TKIs." (PMID 25742484, 2015). "The important molecular targets in cancer chemotherapy are progesterone receptor, cyclooxygenase-2 (COX-2), peroxisome proliferator-activated receptor (PPAR), and epidermal growth factor receptor (EGFR)." (PMID 25741449, 2015). "Furthermore, our data show that GPER and ERα, along with the EGFR/MAPK pathway, contribute to the biological responses to atrazine in diverse cancer cells." (PMID 25616260, 2015). "It is clear from the history of using anti-EGFR monoclonal antibodies (mAbs), including cetuximab, to treat cancer that not all patients benefit from these agents." (PMID 26189560, 2015). "All three of these Sp-regulated genes play a role in cancer cell growth and survival and some studies show that expression of survivin, EGFR and bcl-2 are negative prognostic factors for patients with RCC." (PMID 26035713, 2015). "Receptor tyrosine kinases (RTKs), such as VEGFR, EGFR, and FGFR, are cell signaling effectors that regulate normal development and homeostasis, whose aberrant activities are responsible for many pathological conditions, especially cancers." (PMID 26798565, 2015). "It is important to note that even responders to anti-EGFR therapy routinely develop secondary resistance during anti-EGFR therapy, often by selection of KRAS/NRAS or BRAF-mutant clones arising from a RAS-wildtype cancer." (PMID 26299805, 2015). "Therapies targeting EGFR, one of the most important oncoprotein involved in human cancer, while showing efficacy in other tumors, have not delivered long term benefits to GBM patients." (PMID 26461476, 2015). "Functional interaction between EGFR and IGFBP-3 may also promote chemoresistance in TNBC, and delineating the mechanisms involved may identify additional targets for development of therapies in cancers that express both IGFBP-3 and EGFR." (PMID 26221601, 2015). "EGFR expression in cancer cells is tightly controlled, but the mechanism of the regulation of the EGFR expression is not fully studied." (PMID 25959250, 2015). "Unlike the other agents, ibrutinib did not exhibit any inhibitory effect against wt EGFR-expressing cancer cell lines, which suggests a superior selectivity window." (PMID 26375053, 2015). "Nimotuzumab inhibited EGFR phosphorylation in cancer cells with high/moderate surface expression of EGFR, but not in those with low surface EGFR expression." (PMID 25185971, 2015). "We found that cancer cells with a high basal level of AMPK activity (e.g., UMSCC1 cells) were resistant or minimally responsive to cetuximab-induced growth inhibition despite effective inhibition of cell signaling pathways downstream of EGFR." (PMID 25871473, 2015). "EGFR inhibitors, MEK inhibitors, and BRAF inhibitors can control the growth of cancer cells by abating extra pathway activity, so effects of these drugs partially depend on their ability to control aberrant activity of the pathway due to activating oncogene mutations." (PMID 26220863, 2015).